GJB2 (gap junction protein beta 2)
Diseases named in the same sentence as GJB2 in open-access papers (continued):
Sharing a sentence is not in itself a finding about the gene and the disease.
hearing loss (continued). "Mutations in three connexin (Cx) genes, GJB2 (Cx26), GJB6 (Cx30), and GJB3 (Cx31), have been identified and are known to cause hearing impairment." (PMID 19366456, 2009). "It has taken to the assumption that gene Cx26 or GJB2, with only one exon, codifies protein connexin 26 (226 amino acids), which can be responsible for both forms of hearing loss." (PMID 16446920, 2005). "Truncating mutations in GJB2 typically cause severe-profound hearing loss (HL) phenotypes, whereas non-truncating alleles are often associated with milder or progressive phenotypes." (PMID 41516362, 2026). "STRC pathogenic variants account for 4.08% of GJB2-negative congenital hearing loss cases and represent 14.36% of mild-to-moderate hearing loss patients, with biallelic deletions comprising approximately 70% of all STRC pathogenic alleles." (PMID 41562875, 2025). "The aim of this study was to assess the added benefit of newborn genetic screening for GJB2 and SLC26A4 variants in conjunction with newborn hearing screening in a large cohort of children followed for hearing loss at a Canadian pediatric tertiary healthcare center." (PMID 40008839, 2025). "Non-confirmatory diagnoses with monoallelic pathogenic variants are not uncommon in genetic testing for conditions such as GJB2-related hearing loss." (PMID 40346465, 2025). "Dominant-negative mutations of GJB2, such as R75W, cause syndromic hearing loss and palmoplantar keratoderma." (PMID 40059830, 2025). "Children with known variants of GJB2 and SLC26A4 were identified from 485 children with hearing loss who underwent testing with Next Generation Sequencing (NGS) between January 2015 and February 2018, prior to expanded screening for genetic variants and congenital CMV." (PMID 40008839, 2025). "Our results suggest a therapeutic opportunity for AAV-mediated base editing for the treatment of dominant-negative GJB2-related hearing loss or skin diseases not possible with gene-replacement therapy." (PMID 40059830, 2025). "Being most likely GJB2 the gene causative for hearing loss, these patients were not submitted to ES." (PMID 40121402, 2025). "Although previous studies have identified genetic factors such as mutations in SLC26A4 and GJB2 as contributors to age-related hearing loss, our study did not include genetic testing." (PMID 39834439, 2025). "Consequently, from a mechanistic standpoint, GJB2: c.551G>A is likely to induce syndromic hearing impairment." (PMID 40336802, 2025). "Previous reports have called attention to an apparently increased prevalence of GJB2 carriers relative to the general population in probands that undergo genetic testing for hearing loss and test negative." (PMID 41367487, 2025). "Our findings suggest that the GJB2 c.551G>A variant can result in both syndromic and non-syndromic forms of hearing loss." (PMID 40336802, 2025). "This is particularly relevant when the sequencing of the most frequently involved gene, namely GJB2, shows a mutation which is not known to cause hearing loss." (PMID 38397306, 2024). "For the most common gene in hearing loss population, one case had GJB2 compound heterozygous mutation, with infant onset bilateral profound hearing loss and presence of otoacoustic emission (OAE), and two cases found GJB2 heterozygous mutation (1,507,400 and 1,006,855)." (PMID 38456936, 2024). "We conducted GS on 46 hearing loss families with previously negative ES results and an additional cohort of 36 patients with a monoallelic pathogenic variant in GJB2 (the most common deafness gene)." (PMID 40225913, 2024). "The 35delG mutation, one of the most common mutations of the GJB2 gene, usually causes prelingual, bilateral mild to profound, nonprogressive sensorineural hearing loss." (PMID 38734626, 2024). "Known pathogenic variants in MYO15A, GJB2, and USH2A were most likely to be causal of hearing loss." (PMID 39062005, 2024).
hearing loss (continued). "Our study confirms the wide heterogeneity of ARHL, since causative variants were found in 24 different known hearing loss genes and, besides causative variants in GJB2, there was not a single recurrent pathogenic variant causing hearing loss in this sample." (PMID 39498320, 2024). "Firstly, based on the ACMG guidelines for screening for genes associated with hearing loss, the absence of mutation in GJB2 was investigated in both patients (IV.1 and IV.2)." (PMID 37803361, 2023). "For ~70% of NSNHL patients from the total patient cohort (78/111), in ~75% (63/84) of Ossetians and half (6/12) of Russians the molecular cause of hearing loss was not related to the GJB2 gene." (PMID 36743950, 2023). "The high prevalence of GJB2 mutations in the hearing loss population is evident regardless of ethnic differences." (PMID 34599366, 2022). "In our study, we targeted the limited 20 common variants in GJB2, SLC26A4, 12SrRNA and GJB3 by NGS on universal hearing loss genetic screening for newborns in Jiangxi Province, which showed the advantages of cost efficiency, high throughput and easy interpretation." (PMID 36389375, 2022). "This study aimed to identify the genetic causes of hearing loss (HL) in a family with Iranian Azeri Turkish ethnicity negative for gap junction beta-2 (GJB2), gap junction beta-6 (GJB6), and mitochondrially encoded 12S rRNA (MT-RNR1) deleterious mutations." (PMID 35101039, 2022). "We investigated hearing impairment (HI) in 51 families from Ghana with at least two affected members that were negative for GJB2 pathogenic variants." (PMID 35440622, 2022). "To see whether nuclear genes (GJB2, GJB3, GJB6, and TRMU) mutations played active roles in clinical expression of hearing impairment, we initiated a mutational analysis of the exons of GJB2, GJB3, GJB6, and TRMU in matrilineal relatives of this pedigree." (PMID 34811812, 2022). "We detected variants in different genes, but intronic variants were surprisingly detected in the GJB2 gene of two patients, which offered a possible explanation for the patients’ hearing loss; these variants are in the UTR5 ́region of GJB2—the c.-22-2 and c.-22-6." (PMID 34062854, 2021). "The diagnostic yield of the WES in patients with hereditary hearing loss ranged from 20% for patients where GJB2 variants were already excluded to around 40% for non-pretested patients." (PMID 34062854, 2021). "Xu and Nicholson (2013) analyzed the distribution of the reported GJB2 mutations associated with nonsyndromic hearing loss and revealed that TM2 domain of Cx26 shows the highest density of them (67%), followed by TM3 (50%), E2 (43%), TM4 (40%), NT, and CL (36%), TM1 and E1 (33%)." (PMID 33466560, 2021). "The frequency of GJB2 heterozygotes in healthy individuals (2.2%) is more relevant to the Czech population than the GnomAD NFE (1.9%) and is not too far from a previously found frequency of 4% among those with hearing loss." (PMID 34062854, 2021). "No molecular study of the connexin 26 (GJB2) genes was reported in Iraqi patients with non-syndromic sensorineural hearing loss." (PMID 35126756, 2021). "For instance, it has been demonstrated that patients with the same GJB2 genotype may exhibit wide variations in severity of hearing impairment." (PMID 34943631, 2021). "For GJB2 gene variants, the most frequent etiological factor of nonsyndromic hereditary hearing loss, the hotspots were described as c.235delC and c.109G>A, common in Asian, c.35delG, found in European, and c.71G > A, predominant in the Indian." (PMID 34335733, 2021). "Furthermore, mutations in GJB2, GJB3, GJB6 and TRMU were implicated to be associated with hearing impairment." (PMID 32400865, 2020). "We selected for further study the patients to which the GJB2 mutations did not explain their hearing impairment and the patients with variants in WFS1 gene." (PMID 33333757, 2020).
hearing loss (continued). "Variations in GJB2 gene account for up to 50% of all genetically caused non-syndromic hearing loss cases in Caucasians." (PMID 30837189, 2020). "For the first time, we analyzed the informative parameters of nine predictive in silico tools, obtained by predictions of the clinical significance of missense variants of GJB2 (Cx26), GJB6 (Cx30), and GJB3 (Cx31) connexin genes associated with hearing impairment." (PMID 31015822, 2019). "This study aimed to identify different mutations in the GJB2 gene in patients with severe to profound nonsyndromic sensorineural hearing loss of putative genetic origin, and who were negative or heterozygote for the 35delG mutation." (PMID 29773520, 2019). "After screening out common andnonpathogenic variants, homozygosity for the c.235delC variant (rs80338943, a knownpathogenic variant, NM_004004.5) in the GJB2 gene was found, and therewere no other potentially causative variants for hearing loss." (PMID 30816908, 2019). "A combination of one TMPRSS3 (c.208delC) and one GJB2 (c.35delG) variant was detected in the proband’s maternal uncle, who does not have hearing impairment." (PMID 31412945, 2019). "The mutational spectrum of hearing loss in the population of Indochina Peninsula has not been studied yet; to the best of our knowledge, only information regarding the prevalence of GJB2 variants in Thailand is available." (PMID 30733538, 2019). "As shown in the results for the 208 salivary samples collected from the sporadic moderate-to-profound hearing loss patients, GJB2 and SLC26A4 contributed most mutations, of which, 235delC in GJB2 (43/95, 45.3%) and c.919-2A > G in SLC26A4 (33/95, 34.7%) appeared to be the most common mutations." (PMID 28225033, 2017). "In this study, we identified a novel dominantly inherited c.524C > A mutation, which leads to p.P175H conversion in the GJB2 gene, in a Chinese family with ADNSHL, which is predictive of a decrease in the age of diagnosis and an increase in severity of hearing impairment in successive generations." (PMID 28102197, 2017). "Variations in SLC26A4 and GJB2 in 28 children with bilateral severe-to-profound non-syndromic hearing loss (NSHL) without familial history were analyzed using Sanger sequencing." (PMID 28383030, 2017). "According to genetic detections of GJB2, SLC26A4, and mtDNA12SrRNA via the SNPscan assay, the fact that almost half of the patients with nonsyndromic hearing loss appeared to have a genetic etiology shows that the SNPscan assay is an available diagnosis tool for studies on genetic hearing loss." (PMID 27247933, 2016). "Finally, we provide important evidence of the association of SNPs in the GJB2 and GJB6 genes with hearing loss." (PMID 26075227, 2015). "The importance of gap junctional communication for auditory function has been highlighted by the discoveries that mutations in GJB2 (coding for CX26), GJB6 (CX30) and GJB3 (CX31) may all cause hereditary hearing loss." (PMID 25381570, 2015). "This is the only CNV that has previously been reported to be associated with mild to moderate hearing impairment in GJB2 mutation negative probands." (PMID 25528277, 2014). "Subjects did not have pathogenic GJB2 mutations (the gene most often associated with inherited hearing loss), mitochondrial m.1555A>G or 3243A>G mutations, enlarged vestibular aqueduct, or auditory neuropathy." (PMID 24164807, 2013). "However, the test evaluates only few major genes, such as GJB2, SLC26A4 and mitochondrial genes, and is unable to detect other genetic causes of hereditary hearing loss." (PMID 22938506, 2012). "GJB2 has been shown to be a common gene involved in congenital hearing impairment." (PMID 22899989, 2012). "DFNB1 also harbors the second most common ARNSHL causing mutation, a 309 kb deletion of GJB6, often found in trans with mutations in GJB2, giving rise to a digenic inheritance of this form of hereditary hearing loss." (PMID 21726435, 2011).
hearing loss (continued). "Although molecular analysis of hearing loss is not frequent in developing countries, it is essential to investigate GJB2 and GJB6 gene mutations for public health and genetic counseling purposes." (PMID 20835527, 2010). "However, few studies have examined the noncoding exon 1 of GJB2 in Chinese hearing-impaired patients, and even fewer studies have investigated the promoter region of this gene." (PMID 21122151, 2010). "We also tested the IVS1+1G>A mutation in 262 unrelated nonsyndromic hearing loss patients without GJB2 ORF mutation and 105 normal controls, but neither homozygous IVS1+1G>A mutation nor heterozygous IVS1+1G>A mutation was found." (PMID 21122151, 2010). "All of the 212 unrelated patients with monoallelic GJB2 coding region mutation as well as the 262 unrelated nonsyndromic hearing loss patients without GJB2 coding region mutation showed bilateral moderate to profound sensorineural hearing loss." (PMID 21122151, 2010). "The three most significantly associated SNPs for hearing loss are all located at the GJB2/GJB6 locus on 13q12.1, including rs870729 near GJB6 (p = 3.38×10−11, OR: 1.69), rs3751385 within GJB2 (p = 1.50×10−9, OR: 1.63), and rs7329467 within GJA3 (p = 6.87×10−8, OR: 1.68)." (PMID 20126254, 2010). "The percent of postlingual hearing loss in the 262 nonsyndromic hearing loss patients group without GJB2 coding region mutation is 8%(21/262) and that of preligual is 92% (241/262)." (PMID 21122151, 2010). "Two hundred and sixty-two nonsyndromic hearing loss patients without GJB2 mutation and 105 controls with normal hearing were also tested for the GJB2 IVS1+1G>A mutation by sequencing." (PMID 21122151, 2010). "In monoallelic cases with mutation in gene GJB2, it is not possible to exclude interactions between mutations in the conexin 26 gene and in other genes related to hearing loss in a digenic inheritance pattern." (PMID 19082351, 2008). "However, several studies have reported that 10–50% of symptomatic individuals possess a single heterozygous truncating GJB2 allele, which is generally presumed to function as a null allele and would not be expected to cause hearing loss in isolation." (PMID 41516362, 2026). "We previously reported that CX26 regulates the accumulation of gap junction components and the assembly of gap junctions in the cell-cell junctions between cochlear supporting cells and that mutation of GJB2 leads to fragmentation of GJPs, resulting in hearing loss." (PMID 40059830, 2025). "The c.109G > A (p.Val37Ile) variants in GJB2 is classified as pathogenic for autosomal recessive nonsyndromic hearing loss, exhibiting variable expressivity and incomplete penetrance, according to the ClinGen Hearing Loss Expert Panel." (PMID 39777619, 2025). "Molecular tests found a pathogenic variant in GCK gene, confirming GCK-MODY diabetes and additionally a heterozygous pathogenic variant in the GJB2 gene that identified the patient as a carrier of nonsyndromic hearing loss, and a heterozygous variant in the WFS1 gene (c.68C>T)." (PMID 39766859, 2024). "In addition, differentiated cells from iPSCs of CX26‐deficient mice also had the potential to form GJPs with dramatically fragmented small vesicle‐like GJPs, which is a major pathological feature of GJB2‐associated hearing loss." (PMID 39188517, 2024). "Variants of the gap junction protein beta-2 (Gjb2) and gap junction protein beta-6 (Gjb6) genes, encoding connexin 26 (Cx26) and connexin 30 (Cx30), respectively, have been linked to the deafness DFNB1, the most frequent non-syndromic hearing loss in the Mediterranean population." (PMID 36829891, 2023). "However, some studies have shown that the hearing loss caused by Gjb2 mutation occurs before the degeneration of hair cells, which also indicates that the K+ circulation is not the pathogenic mechanism of GJB2-related hearing loss." (PMID 37333892, 2023). "The presence of at least one non-truncating GJB2 variant causes a milder course of hearing loss." (PMID 36579563, 2022).
hearing loss (continued). "Furthermore, mutations in Cx26 gene (GJB2) in humans, in addition to cause hearing loss, lead to the development of skin and primary breast tumors, suggesting again that the alterations of Cx26 functionality may predispose to cancer." (PMID 33837873, 2021). "Although GJB2 and SLC26A4 mutations account for a large part of causes of hereditary deafness, there are still a large number of known or unknown gene mutations that cause hearing loss." (PMID 34335733, 2021). "In the current study, we selected four different missense GJB2 mutations, which result in either syndromic or non-syndromic hearing loss, in order to compare and contrast their cellular localization and function in auditory cells before and after Cx43 ablation." (PMID 32300592, 2020). "The results showed that individuals without hearing loss had c.487A>G variant in GJB2 gene." (PMID 30989077, 2019). "The genetic testing for GJB2 variant among partners who wish to marry each other and has hearing impairment will predict the possibility of having a hearing impaired child if other genetic and non-genetic causes of hearing loss can be ruled out." (PMID 30989077, 2019). "However, studies with the Brazilian population have shown that the screening of the GJB2 and GJB6 genes explains the etiology of hearing loss (HL) in only 1–24.7% of the subjects analyzed, being the c.35delG (rs80338939) mutation in GJB2 (NM_004004.5) gene, the most frequent pathogenic variant." (PMID 30068397, 2018). "Finally, the mean European ancestry of African carriers of GJB2-related nonsyndromic hearing loss is 23.0%, while the mean European ancestry of non-carriers is 12.2% (P = 0.01)." (PMID 29179688, 2017). "Variations in GJB2 may cause either autosomal dominant or recessive non-syndromic hearing loss (NSHL) as well as syndromic hearing loss (SHL)." (PMID 28102197, 2017). "We reviewed the available studies on the aetiology and genetics of hearing loss in Africa, including our previous publications on this topic that have shown the non-implication in Africansof the genes most commonly associated with ARNSHL among patients of European and Asian descent: GJB2 and GJB6." (PMID 26185573, 2015). "Here we show in the participating extended family a homozygous mutation c.506G>A, (TGC>TAC) p.Cys169Tyr, in the GJB2 gene, which could be proven for the first time and led to nonsyndromal severe hearing impairment in the afflicted patients." (PMID 24551843, 2014). "Contrary to GJB2 mutations causing autosomal recessive non-syndromic hearing loss (HL) which are ethnically specific because of founder effect in some specific populations, GJB2 mutations responsible for syndromic hearing loss seem not to be population specific." (PMID 23924173, 2013). "In the present study we selected Japanese subjects that had hereditary hearing loss without GJB2 mutations, mitochondrial mutations, enlarged vestibular aqueduct or auditory neuropathy-associated OTOF mutations, and we aimed to detect the spectrum of rare deafness genes in these patients." (PMID 24164807, 2013). "Though most cases of GJB2-associated hearing impairment are congenital, a small number of individuals with bi-allelic GJB2 mutations have been reported who initially passed the NHS but were subsequently identified with hearing loss in their infancy or early childhood." (PMID 22574200, 2012). "Involvement of GJB2 noncoding regions in hearing loss (HL) has not been extensively investigated." (PMID 22567369, 2011). "Indeed, the absence of mutation in the GJB2 gene in those subjects with hearing impairment indicated that the GJB2 gene did not contribute to the deafness phenotype in those subjects." (PMID 21205314, 2011). "Thus, 29.23% (83/284) of the unrelated families of deaf patients in typical areas in China had molecular defects in GJB2, and 18.31% (52/284) had confirmed molecular etiology of nonsyndromic hearing impairment (51 autosomal recessive and 1 autosomal dominant) in the GJB2 gene." (PMID 19744334, 2009).